RPGRIP1L (RPGRIP1 like)
Description:
Negatively regulates signaling through the G protein-coupled thromboxane A2 receptor (TBXA2R). May be involved in mechanisms like programmed cell death, craniofacial development, patterning of the limbs, and formation of the left-right axis (By similarity). Involved in the organization of apical junctions; the function is proposed to implicate a NPHP1-4-8 module. Does not seem to be strictly required for ciliogenesis. Involved in establishment of planar cell polarity such as in cochlear sensory epithelium and is proposed to implicate stabilization of disheveled proteins (By similarity). Involved in regulation of proteasomal activity at the primary cilium probably implicating association with PSDM2 (By similarity).
Synonyms: FTM; KIAA1005; NPHP8; CORS3; JBTS7; MKS5; PPP1R134; COACH3
Tractability: Antibody: its Gene Ontology location is reachable by antibodies, with high confidence. PROTAC: ubiquitination databases record sites on it.
Gene: Protein-coding gene on chromosome 16 (53,598,153 to 53,703,938, reverse strand). Ensembl gene ENSG00000103494.
Subcellular location: Cytoplasm; Cytoplasm, cytoskeleton, cilium basal body; Cytoplasm, cytoskeleton, cilium axoneme; Cytoplasm, cytoskeleton, microtubule organizing center, centrosome; Cell junction, tight junction
Subcellular location (Human Protein Atlas): Cytosol; Plasma membrane; Basal body; Primary cilium
Pathways (Reactome):
Organelle biogenesis and maintenance: Anchoring of the basal body to the plasma membrane
Signal Transduction: Hedgehog 'off' state
Gene Ontology:
Molecular function: protein binding; thromboxane A2 receptor binding
Biological process: negative regulation of G protein-coupled receptor signaling pathway; non-motile cilium assembly; protein localization to ciliary transition zone; retinal rod cell development; regulation of signal transduction
Cellular component: axoneme; cell-cell junction; centrosome; ciliary basal body; ciliary transition zone; cilium; cytoplasm; cytosol; NPHP complex; photoreceptor connecting cilium; bicellular tight junction
Genetic constraint (gnomAD): Loss-of-function variants: 89 observed, 117.01 expected, observed/expected ratio (o/e) 0.76, 90% interval 0.64 to 0.91. The upper end of that interval is the gene's LOEUF score, 0.91, which puts it in group 3 of 6, group 1 being the genes least tolerant of losing a copy. Missense variants: 1,147 observed, 1,245.5 expected, observed/expected ratio (o/e) 0.92, 90% interval 0.88 to 0.97. Synonymous variants: 403 observed, 431.29 expected, observed/expected ratio (o/e) 0.93, 90% interval 0.86 to 1.01.
Gene-disease validity (ClinGen):
ClinGen rates the evidence that RPGRIP1L causes each of these diseases.
ciliopathy (autosomal recessive): Definitive. A genetic disorder of the cellular cilia or the cilia anchoring structures, the basal bodies, or of ciliary function.
Homologues: Orthologues: chimpanzee RPGRIP1L (96% identical), macaque RPGRIP1L (93% identical), dog RPGRIP1L (87% identical), rabbit RPGRIP1L (87% identical), pig RPGRIP1L (86% identical), guinea pig RPGRIP1L (82% identical), mouse Rpgrip1l (82% identical), rat Rpgrip1l (81% identical), tropical clawed frog rpgrip1l (54% identical), zebrafish rpgrip1l (49% identical), Caenorhabditis elegans mks-5 (16% identical), Caenorhabditis elegans C09G5.13 (5% identical). Paralogues in human: RPGRIP1 (32% identical).
Diseases named in the same sentence as RPGRIP1L in open-access papers:
RPGRIP1L is named in the same sentence as 71 diseases in open-access papers, as found by Europe PMC text mining. Sharing a sentence is not in itself a finding about the gene and the disease. The quoted sentences say what the papers report.
ciliopathies (37 papers, 2010 to 2025). "RPGRIP1L gene mutations are associated with different ciliopathies mostly due to impairment of protein degradation and protein processing by UPS." (PMID 35646931, 2022). "Loss of function mutation of RPGRIP1L impairs the proteasomal activity at ciliary compartment, thus contributing to ciliopathy phenotype." (PMID 35646931, 2022). "Mutations in RPGRIP1L cause ciliopathies associated with severe embryonic defects, such as Meckel-Gruber Syndrome (MKS)." (PMID 36061204, 2022). "The protein RPGRIP1L, encoded by the Rpgrip1l/Ftm/Mks5/Nphp8 (Rpgrip1-like) gene and mutated in patients suffering from deadly ciliopathies, is located in the primary cilium transition zone and controls autophagy by inhibiting mTOR signaling." (PMID 36438551, 2022). "RPGRIP1L (a ciliary TZ protein mutated in a range of ciliopathies including MKS and JBTS) has been reported to interact with the proteasome proteins, PSMD3 and PSMD5." (PMID 35170427, 2022). "A direct link between dysfunctional UPS and ciliopathies has been established by identifying loss-of function mutations of RPGRIP1L (RPGRIP1 like) that are causally linked to Joubert syndrome and Meckel syndrome." (PMID 35646931, 2022). "Curiously, mutations in RPGRIP1L in the NPHP complex can be associated with more severe ciliopathies such as Meckel-Gruber syndrome and JS and/or modify retinal degeneration phenotype in ciliopathies." (PMID 32747192, 2021). "The loss of function mutations in these proteins not only disrupts their interactions with RPGRIP1L, but was also associated with aberrant ciliogenesis and ciliopathies." (PMID 33808286, 2021). "The SNP with the most significant p-value in our scan in RPGRIP1L, rs61747071, is a missense loss-of-function mutation A229T that has been shown to lead to photoreceptor loss in ciliopathies." (PMID 32469896, 2020). "Among the mutant lines in this study we found five genes which have been previously linked to human ciliopathies: B9d2, Cc2d2a, Rpgrip1l, Ift140 and Nek930." (PMID 31243271, 2019). "For example, an allele of RPGRIP1L enhances retinal degeneration across a spectrum of ciliopathies and mutations in AHI1 were suggested to increase the severity of photoreceptor degeneration in nephronophthisis patients." (PMID 30970040, 2019). "To evaluate the meaning of the protein axis Nphp4‐Invs‐Nphp1 in the development of ciliopathies caused by mutations in Rpgrip1l, we investigated the phenotype of Nphp4−/− mouse embryos." (PMID 29650680, 2018). "Transition zone-localised RPGRIP1 and RPGRIP1L represent additional examples of very closely related ciliopathy proteins linked to a broad tissue pathogenesis (RPGRIP1L), versus a retinal-specific disease (RPGRIP1)." (PMID 27930654, 2016). "The highest intensity points of TMEM67 and TCTN2 occurred at the same axial level as MKS1 and RPGRIP1L, indicating a special axial level accommodating these ciliopathy-associated proteins." (PMID 26365165, 2015). "A common variant in the RPGRIP1L protein, A229T, was recently reported to be associated with the presence of retinopathy in a cohort of syndromic ciliopathy patients." (PMID 21857984, 2011). "A case in point is the allele A229T of RPGRIP1L, which has been found to be enriched in SLSN patients, can intensify the development of retinal degeneration by decreasing the stability of RPGRIP1L-RPGR complexity in the context of mutations in specific ciliopathy proteins." (PMID 40427560, 2025). "Remarkably, mutations in RPGRIP1L result in severe human ciliopathies." (PMID 35543155, 2022). "Indeed, defects in the human RPGRIP1L gene were associated with the ciliopathies Joubert syndrome 7 and Meckel syndrome type 5." (PMID 33808286, 2021). "The Ftm/Rpgrip1l gene encodes a protein involved in the formation and function of the primary cilium, a sensory organelle projecting from the cell surface with multiple functions in development and whose defects cause human syndromes called ciliopathies." (PMID 31521111, 2019).
ciliopathies (continued). "Mutations in the RPGR gene and its interacting partners, RPGRIP1 and RPGRIP1L, cause ciliopathies, but the function of their proteins remains unclear." (PMID 29796181, 2018). "Similarly, NEK4 interacts with the known ciliopathy protein RPGRIP1L (mutations in RPGRIP1L are causative for Joubert and Meckel-Gruber syndromes), is localized to the basal body in ciliated cells, and its deficiency impairs cilium assembly." (PMID 27894351, 2016). "In this context, it should be taken into consideration that the severe ciliopathy phenotype of Rpgrip1l−/− mouse embryos and also the severe human ciliopathies which are caused by mutations in RPGRIP1L could be based on more molecular processes than the TZ assembling alone." (PMID 29650680, 2018). "Here, we use pluripotent stem cell-derived spinal organoids to reveal distinct functions of the ciliopathy gene RPGRIP1L in humans and mice, and uncover an unexplored role for cilia in human axial patterning." (PMID 40188187, 2025). "Like RPGRIP1L, the human CEP290 gene encodes a TZ protein and its mutation leads to severe neurodevelopmental ciliopathies." (PMID 39388365, 2024). "Homozygous missense mutations, frameshift, and splice-site mutations in RPGRIP1L have been reported in individuals with JBTS, another severe ciliopathy." (PMID 36061204, 2022). "This suggestion is supported by the biochemical interaction of another ciliopathy protein, Rpgrip1l, with proteasome proteins and the discrete localisation of ubiquitin at the ciliary base." (PMID 35170427, 2022). "Recessive mutations in RPGRIP1L, which is a homolog of RPGRIP1, can cause systematic ciliopathies like Joubert syndrome-7, Meckel syndrome 5, and COACH syndrome 3, which also involve intellectual disability." (PMID 34722527, 2021). "Here we studied development of the diencephalon, hypothalamus and eyes in mutant mice in which the Ftm/Rpgrip1l ciliopathy gene is disrupted." (PMID 30692221, 2019). "Previous studies revealed a ciliopathy phenotype of Rpgrip1l−/− murine embryos, which die, at the latest around birth, whereas Rpgrip1l+/− mice are viable and healthy." (PMID 29650680, 2018). "A known modifier of ciliopathies (RPGRIP1L) has been functionally tested in zebrafish to observe the modifying effects of different alleles." (PMID 23559858, 2013). "RPGRIP1L is involved in processes like ciliopathies, Hedgehog signaling, and autophagy." (PMID 39165421, 2024). "Additionally, polymorphic variation in RPGRIP1L has been shown to be a modifier of retinal degeneration in ciliopathies." (PMID 36061204, 2022). "Rpgrip1l is essential for the TZ localization of many other ciliopathy proteins." (PMID 30692221, 2019). "In this paper we study the role of the Ftm/Rpgrip1l ciliopathy gene in mouse forebrain development." (PMID 30692221, 2019). "We provide compelling evidence that RPGR, RPGRIP1 and RPGRIP1L may function in ciliopathy by regulating the activity of proteasome and mediating SOCE." (PMID 29796181, 2018). "Due to all these data and since the TZ amount of Cep290 was reduced in all analysed Rpgrip1l−/− mouse cell types, Cep290 might be an important factor in the development of the very severe ciliopathy of Rpgrip1l−/− mouse embryos." (PMID 29650680, 2018). "The 229T allele of RPGRIP1L has a possible role in the development of RP in patients with ciliopathy, but we were not able to document any influence on the phenotype of our patients." (PMID 22876109, 2012). "Mutations in RPGRIP1 cause Leber congenital amaurosis (LCA6 [MIM 605446]) and cone-rod dystrophy (CORD13 [MIM 608194]), and mutations in RPGRIP1L cause Joubert syndrome (JBTS7 [MIM 611560]) and Meckel syndrome (MKS5 [MIM 611561]), two syndromic ciliopathies with associated retinal dystrophy." (PMID 21857984, 2011). "Consequently, the very severe ciliopathy phenotype of Rpgrip1l−/− mouse embryos is not or not solely caused by the reduced Nphp4 amount in the absence of Rpgrip1l." (PMID 29650680, 2018).
ciliopathies (continued). "We also observed that knockdown of ciliopathy genes ALMS1, BUBR1 [BUB1B], IFT80, NPHP1, NPHP8 [RPGRIP1L], TCTN2, TMEM216 and TUB retarded neuronal migration." (PMID 26206566, 2015). "At least two polymorphic markers per gene (rs1718031 and rs729386 for NPHP1; rs1041480 and rs2064430 for AHI1; rs2061589 and rs1508595 for CEP290; rs1990637 and rs1946155 for RPGRIP1L; rs1483457 and rs911 for TMEM67) were inconsistent with linkage in Ciliopathy-672." (PMID 22002901, 2011). "Here, we show that RPGRIP1L is not required for SHH activation or motoneuron lineage commitment in human spinal progenitors and that this feature is shared by another ciliopathy gene, TMEM67." (PMID 40188187, 2025).
Obesity (25 papers, 2013 to 2024). Accumulation of substantial excess body fat. "Another cilia transition zone protein, retinitis pigmentosa GTPase regulator-interacting protein-1 like (RPGRIP1L), is also implicated in feeding, as conditional ablation of RPGRIP1L leads to obesity in mice." (PMID 36568981, 2022). "Efforts have been made to understand the biological mechanisms underlying body weight regulation: SNPs in FTO are believed to be associated with obesity through an effect on RPGRIP1L." (PMID 31075924, 2019). "As it has been proposed that IRX3 and RPGRIP1L are primarily responsible for the enhanced obesity associated with the obesity-related SNPs in FTO12, 13, we compared mRNA levels of FTO, IRX3 and RPGRIP1L in WT gWAT and MEFs." (PMID 25881961, 2015). "Interestingly, Speakman indicated that FTO gene polymorphisms mediate their obesity effects via nearby genes such as RPGRIP1L and IRX3." (PMID 34399781, 2021). "Reports from another study indicated that RPGRIP1L may be partly or exclusively responsible for the obesity susceptibility signal at the FTO locus." (PMID 31075924, 2019). "CNS abnormalities caused by RPGRIP1L haploinsufficiency may cause obesity in humans." (PMID 36101325, 2022). "For example, hypomorphisms in the cilia gene Rpgrip1l, found within the fat mass and obesity-associated FTO locus, have been shown to cause obesity." (PMID 38353726, 2024). "Additional cilia genes that are associated with obesity include CEP19, CEP290, MC4R, ADCY 3, and RPGRIP1L." (PMID 36568981, 2022). "Congenital RPGRIP1L hypomorphism in POMC neurons leads to hyperphagic obesity and increased adiposity; however, deletion of RPGRIP1L in adult POMC neurons did not result in an obesity phenotype." (PMID 36568981, 2022). "As with Fto, perturbing the expression of these genes in mice results in a bodyweight phenotype, with homozygous deletion of Irx3 resulting in a smaller mouse while heterozygous deletion of Rpgrip1l leading to a mild obesity phenotype." (PMID 25830092, 2015). "Targeted deletion of Irx3 in mice results in reduced body size and resistance to HFD-induced obesity, whereas mice heterozygous for a deletion in Ftm (also Rpgrip1l) results in increase of body-weight." (PMID 25242086, 2014). "Recent studies have shown that the obesity‐associated SNPs embedded in the first intron of FTO are influencing expression of different, distant genes, called RPGRIP1L and IRX3, instead of affecting FTO itself." (PMID 25501432, 2014). "While human GWAS reported FTO as the major candidate gene for the obesity associated genomic region, additional significant SNPs were located in the close neighborhood of FTO, in particular, in the RPGRIP1-like (RPGRIP1L) gene." (PMID 23691044, 2013). "RPGRIP1L represents a particularly interesting target, as its expression and activity are regulated by intronic variants located in the FTO gene (which is strongly associated with obesity and T2D) through long-range regulation." (PMID 31754094, 2019). "Indeed, recent data focussing on obesity associated variants within FTO have implicated two neighbouring genes, RPGRIP1L and IRX3, as having a functional link between the SNP and the observed human phenotypes." (PMID 25830092, 2015). "The intronic SNPs associated with human obesity may influence adiposity through effects on the expression of other neighbouring genes including IRX3 and RPGRIP1L." (PMID 25830092, 2015). "One of the most accepted hypotheses to explain the molecular mechanism takes into consideration that the expression regulation of FTO and other nearby genes (RPGRIP1L and IRX3) is a process controlled by an obesity‐associated region in intron 1 of FTO, which we also replicated in this study." (PMID 31033179, 2019). "The fact that the obesity-associated FTO SNPs are intronic has led to the notion that the SNPs may affect obesity through influencing the expression of genes proximal to FTO in the locus, namely, RPGRIP1L, IRX3, and IRX5." (PMID 26788058, 2015).
Obesity (continued). "A genomic region on OCU5 was associated with C16:0, SFA, PUFA, and PUFA/SFA fatty acids and included two important candidate genes directly related to lipid metabolism, binding, and obesity (FTO and RPGRIP1L)." (PMID 37835677, 2023). "More research needs to be conducted to clarify the role of RPGRIP1L and IRX3 in obesity and their relation to FTO." (PMID 25501432, 2014). "CUX1-mediated upregulation of RPGRIP1L by binding to FTO intron 1 may reduce leptin sensitivity and lipolysis, promoting the development of obesity." (PMID 39125332, 2024). "In addition, it was reported that the FTO gene realizes its effect on body composition and obesity in interaction with other genes, such as FTM (RPGRIP1L) and Irx3, which are localized near it." (PMID 31810473, 2019). "A recent report revealed that SNPs in FTO could influence obesity by altering the expression of the adjacent genes IRX3 and RPGRIP1L." (PMID 28208657, 2017). "However, there are reports that obesity-associated SNPs are not functionally related to FTO, but are related to FTO neighboring genes IRX 3 and RPGRIP1L." (PMID 34638947, 2021). "Some recent studies have suggested that the association between FTO SNPs in intron 1 and obesity might be owing to their potential influence on expression of IRX3, IRX5, and RPGRIP1L, rather than on their expression of FTO." (PMID 30105001, 2018). "While it remains controversial as to whether the obesity-related SNPs in FTO act via modulation of FTO function or by influencing adjacent genes such as IRX3 and RPGRIP1L, our results provide firm evidence that FTO modulates adipogenesis, and thereby fat mass, both in vitro and in vivo." (PMID 25881961, 2015). "Regardless of whether the obesity-associated SNP affects FTO expression levels, these studies have clearly proven an important role of FTO in the regulation of body weight, independent of IRX3, IRX5, and RPGRIP1L." (PMID 26788058, 2015).